TREM2 (triggering receptor expressed on myeloid cells 2)
Diseases named in the same sentence as TREM2 in open-access papers (continued):
Sharing a sentence is not in itself a finding about the gene and the disease.
hippocampal atrophy (4 papers, 2018 to 2022). "Additional studies showed that TREM2 deletion is associated with increased tau pathologies and hippocampal atrophy in the presence of Aβ in the TauPS2APP mouse due to disease-associated microglia activation that is Aβ- and TREM2-dependent." (PMID 36142483, 2022).
Huntington disease (4 papers, 2013 to 2022). Huntington disease (HD) is a rare neurodegenerative disorder of the central nervous system characterized by unwanted choreatic movements, behavioral and psychiatric disturbances and dementia. "We conclude that neither neurogranin nor TREM2 is a useful biofluid biomarker for disease processes in Huntington’s disease." (PMID 29523800, 2018). "Nonetheless we conclude that neither neurogranin nor TREM2 is likely to be of value as a CSF biomarker for disease processes in Huntington’s disease." (PMID 29523800, 2018).
Hyperglycemia (4 papers, 2020 to 2026). An increased concentration of glucose in the blood. "It remains unknown whether TREM2 modulates hyperglycemia-induced microglial inflammation." (PMID 34356130, 2021). "Pseudotime trajectory analysis indicates a gradual downregulation of Trem2, CCR5, and Cx3cr1, suggesting that chronic hyperglycemia induces functional exhaustion of microglia." (PMID 41484634, 2026). "To determine whether TREM2 regulates high glucose-induced microglial inflammation, we used BV2 cells (immortalized primary microglia) treated with high glucose (35 mM) to mimic hyperglycemia in vitro." (PMID 34356130, 2021). "Similarly, both in vitro and in vivo results showed that hyperglycemia combined with CCH showed a more pronounced inflammatory response, which may be the result of the interaction between TREM-2 and MAPK signals." (PMID 31900229, 2020).
infarction (4 papers, 2018 to 2023). A localised pathological necrosis of tissue resulting from obstruction of the blood supply usually by a thrombus, an embolus, or vascular torsion. "MANF and TREM2 protein abundance is robustly increased after MCAo, and DHA treatment potentiated MANF abundance, decreased TREM2 expression, improved neurobehavioral recovery, reduced infarction, and provided enhanced neuroprotection." (PMID 32757264, 2020). "Expression of TREM2 and CD68 in cerebral infarcts of different ages." (PMID 28987033, 2018).
memory impairment (4 papers, 2020 to 2025). "TREM2-deficiency has been associated with memory impairment in tau transgenic mice, while higher TREM2 expression was neuroprotective and beneficial for memory." (PMID 33032659, 2020). "In addition, triggering receptor expressed on myeloid cells 2 (TREM2) gene has been shown to protect neurons from inflammation and to ameliorate memory impairment in AD mice through interacting with the AKT gene in the PI3K/AKT/FoxO3a signaling pathway." (PMID 33352859, 2020). "This was corroborated in the 5xFAD mouse model of familial AD where CBD treatment ameliorated memory impairment through the regulation of IL33 and TREM2." (PMID 40811673, 2025).
nonalcoholic fatty liver disease (4 papers, 2022 to 2025). "TREM2+ macrophages have been well reported in the liver, where they are protective against non-alcoholic fatty liver disease." (PMID 35848799, 2022).
pneumococcal pneumonia (4 papers, 2014 to 2018). A febrile disease caused by STREPTOCOCCUS PNEUMONIAE. "Knapp’s lab also found that TREM-2 deficiency improved lung pathology and prevented systemic inflammation during pneumococcal pneumonia." (PMID 29887864, 2018). "We conclude that TREM-2 deficiency improved bacterial and apoptotic cell clearance, lung pathology and prevented systemic inflammation during pneumococcal pneumonia, all of which ultimately led to improved survival." (PMID 24945405, 2014). "Ninety five hours post infection, before the first Trem-2−/− mouse succumbed, 60% of WT mice were dead, demonstrating conclusively that WT mice displayed enhanced mortality compared to their TREM-2 deficient counterparts during pneumococcal pneumonia." (PMID 24945405, 2014). "In our study, we unexpectedly found that alveolar macrophage expressed TREM-2 is detrimental in bacterial phagocytosis and clearance during pneumococcal pneumonia." (PMID 24945405, 2014). "Thus, we hypothesized that studying TREM-2 in the context of pneumococcal pneumonia would provide an ideal model system for examining the cross-talk between TLR signaling and phagocytosis within the lungs." (PMID 24945405, 2014).
retinal degeneration (4 papers, 2020 to 2025). Degeneration of the retina. "Its expression is upregulated in human retinal degeneration, and genetic deficiency of Trem2 accelerates disease progression in mouse models by increasing microglial infiltration." (PMID 40716081, 2025). "This study explored the mechanisms underlying the TREM2-mediated protective function of activated microglial cells during retinal degeneration." (PMID 39187498, 2024). "Our study linked TREM2 signaling with PPARγ activation, and provided a potential therapeutic target for the management of retinal degeneration." (PMID 39187498, 2024). "recently identified a Trem2‐positive microglial subset that mitigates retinal degeneration by clearing atrophic debris in retinal degeneration mouse models." (PMID 40716081, 2025). "To further elucidate the role of TREM2 in microglial cell activation and function during retinal degeneration, we induced photoreceptor degeneration using MNU in Trem2−/− mice." (PMID 39187498, 2024). "For example, recent research has shown that TREM2-mediated upregulation of galectin-3, also contributes to the phagocytic activity of microglial cells during retinal degeneration." (PMID 39187498, 2024). "In this study, we utilized chemical-induced and inherited mouse models of retinal degeneration to investigate the characteristics of microglial cell activation and the role of TREM2-mediated microglial cell activity during the process." (PMID 39187498, 2024). "Our findings suggested that the protective effect of microglia during retinal degeneration was dependent on Trem2 expression and carried out via the activation of PPARγ and the consequent upregulation of CD36 expression." (PMID 39187498, 2024). "Taken together, our study underscored the importance of TREM2 in regulating microglia activation, and identified PPARγ signaling and CD36 as potential mechanisms and effector molecules of TREM2 in the context of retinal degeneration." (PMID 39187498, 2024). "Despite extensive studies on microglial cell-expressed TREM2 in neurodegenerative conditions, its role during retinal degeneration remains inadequately explored." (PMID 39187498, 2024). "Out study identified PPARγ as an important mediator of TREM2 activation in microglial cells during retinal degeneration." (PMID 39187498, 2024). "It would be interesting to investigate the involvement of TREM2 in the phagocytosis of photoreceptor cells in models of retinal degeneration." (PMID 36977680, 2023). "Microgliosis is observed in numerous neurological disorders, and only recently evidence has been presented that TREM2‐dependent microglial functions appear to be protective in AD models, AD patients, and models of retinal degeneration." (PMID 32154671, 2020). "N-methyl-N-nitrosourea (MNU)-induced retinal degeneration was established in C57BL/6 J (WT) and Trem2 knockout (Trem2−/−) mice." (PMID 39187498, 2024). "To unveil the underlying mechanism associated with Trem2-deficient microglia and aggravated photoreceptor death during retinal degeneration, we analyzed the downregulated genes in CD11b microbeads-enriched microglial cells of MNU-treated Trem2−/− retina (relative to MNU-treated WT retina)." (PMID 39187498, 2024).
Senile plaques (4 papers, 2019 to 2025). Senile plaques are extracellular deposits of amyloid in the gray matter of the brain. "Phagocytosis and in particular uptake of Aβ—a major component of senile plaques in the AD brain—is a prominent function of microglia, which according to preclinical in vitro and in vivo models is reduced by TREM2 loss of function." (PMID 33613545, 2020). "AD TREM2 mutants may therefore enhance Aβ deposition during the early stage of AD while leading to a reduction in APOE production by microglia and decreased APOE levels in senile plaques suggesting that TREM2 may have protective functions early during amyloidogenesis." (PMID 31649511, 2019).
thyroid cancer (4 papers, 2021 to 2025). "The findings imply that elevated expression of GZMK, TREM2, and OR4D10 is linked to the hyperactivation of several oncogenic pathways in thyroid cancer, including those that regulate cell division." (PMID 40332815, 2025). "Subsequently, the TCGA database results showed the expression of CXCL10, CD40LG, KRT14, TRAT1, and TREM2, with only TREM2 expression levels being upregulated in thyroid cancer (P < 0.05)." (PMID 36438899, 2022). "Western blot results showed that the TREM2 expression was upregulated in thyroid cancer tissues (P < 0.05)." (PMID 36438899, 2022). "The qRT-PCR results indicated that TREM2 was significantly raised in thyroid cancer cells (P < 0.05)." (PMID 36438899, 2022). "To further investigate the mechanism of TREM2 promoting thyroid cancer cell activity, we used western blot to detect the expression of IκB-α, p-IκB-α, NF-κBp65, and p-NF-κBp65 genes in SW579 and KTC-1 cells." (PMID 36438899, 2022). "Subsequently, TCGA database results showed the expression of CXCL10, CD40LG, KRT14, TRAT1, and TREM2, with only TREM2 expression levels being upregulated in thyroid cancer." (PMID 36438899, 2022). "This suggests that the development of thyroid cancer is linked to GZMK, TREM2, and OR4D10." (PMID 40332815, 2025). "According to our research, OR4D10, TREM2, and GZMK could all be genes associated with thyroid cancer." (PMID 40332815, 2025). "It is suggested that TREM2 exerts a pro-proliferative effect on thyroid cancer cells by activating the NF-κB signaling pathway to upregulate the expression of cyclin D1 and Bcl2, indicating that TREM2 may be located upstream of the NF-κB signaling pathway." (PMID 36438899, 2022). "Similarly, the immunohistochemical results showed that the TREM2 expression was mainly localized to the cytoplasm and was expressed in both thyroid cancer tissues and controls, with a significantly higher expression in cancer tissues than in controls." (PMID 36438899, 2022). "TREM2 was linked to M staging and pathological staging, OR4D10 was linked to T, N, and pathological staging, and GZMK was linked to T, N, M, and pathological staging, according to our analysis of the expression of these three proteins in the development of thyroid cancer." (PMID 40332815, 2025). "The current study presents a comprehensive analysis of the expression patterns and potential roles of GZMK, TREM2, and OR4D10 in pan-cancer, with a particular focus on thyroid cancer (THCA)." (PMID 40332815, 2025). "GZMK, TREM2, and OR4D10 were strongly expressed in several kinds of malignancies including thyroid cancer." (PMID 40332815, 2025). "In conclusion, our study provides new insights into the expression patterns and potential roles of GZMK, TREM2, and OR4D10 in pan-cancer, with a particular focus on thyroid cancer." (PMID 40332815, 2025). "In this study, we aimed to comprehensively investigate the expression patterns, prognostic significance, and functional roles of GZMK, TREM2, and OR4D10 in thyroid cancer." (PMID 40332815, 2025). "In particular, THCA thyroid cancer in the TCGA cohort had lower GZMK, higher TREM2, and higher OR4D10 expression compared to the adjacent tissues." (PMID 40332815, 2025). "To further understand the functions and pathways influenced by GZMK, TREM2, OR4D10, and all other mRNAs in thyroid cancer, we performed correlation studies using TCGA data." (PMID 40332815, 2025). "Specifically, in THCA, we observed lower GZMK and higher TREM2 and OR4D10 expression in tumor tissues compared to adjacent normal tissues, suggesting their involvement in thyroid cancer pathogenesis." (PMID 40332815, 2025). "Our findings suggest that GZMK, TREM2, and OR4D10 may play important roles in modulating the immune response in thyroid cancer, potentially through their effects on leukocyte cell–cell adhesion and mononuclear cell differentiation." (PMID 40332815, 2025). "This suggests that GZMK, TREM2, and OR4D10 may be involved in the pathogenesis of thyroid cancer." (PMID 40332815, 2025).
acute pneumonia (3 papers, 2014 to 2021). "Considering that the elimination of pathogens is the crucial step in host defense during pneumonia, we then more closely examined the anti-bacterial properties of macrophages and the role of TREM-2 herein." (PMID 24945405, 2014). "This occurred via the suppressive effects of TREM-2 on complement component 1q (C1q), an important regulator of bacterial phagocytosis that is crucial for the host response during pneumonia." (PMID 24945405, 2014). "Thus, targeting the TREM-2 pathway could be used as a novel strategy for modulating C1q production and pulmonary innate immune responses, which could be of clinical relevance during pneumonia and other respiratory tract infections." (PMID 24945405, 2014). "Since it is not feasible to study TREM-1 and TREM-2 mRNA expression at tissue level in these patients, we used our well-established murine model of pneumonia-derived melioidosis in which mice are intranasally infected with a lethal dose of B. pseudomallei." (PMID 27253382, 2016). "The triggering receptor expressed on myeloid cells 2 (TREM-2) has recently been shown to be both a negative regulator of the inflammatory response and a promoter of phagocytosis, but its contribution to pneumonia remains unknown." (PMID 24945405, 2014).
aortic aneurysm (3 papers, 2022 to 2025). A ruptured aneurysm located in the wall of the proximal portion of the descending aorta proceeding from the arch of the aorta. "The single-cell map of macrophages in aortic aneurysm has been reported, which also reported Trem2 macrophage subpopulations." (PMID 40463378, 2025). "We identified a subpopulation of the Trem2 macrophage featured biological function on macrophage migration and expression of SPP1, TREM2, FABP5, and ANXA2 in both organisms during the pathology of aortic aneurysm." (PMID 36703732, 2022).
bacterial sepsis (3 papers, 2014 to 2025). "Elevated bacteremia in WT mice resulted in enhanced systemic inflammation as determined by plasma IL-6 measurements, compared to TREM-2 deficient mice." (PMID 24945405, 2014). "To further confirm the role of TREM2 in acute inflammation in vivo, we established an LPS endotoxemia model and a PA-induced bacterial sepsis model." (PMID 39405126, 2024). "Additionally, we established an endotoxemia model via LPS injection and a bacterial sepsis model by Pseudomonas aeruginosa (PA) infection to determine TREM2 expression in macrophages." (PMID 39405126, 2024).
cholesteatoma (3 papers, 2016 to 2025). A pathologic process characterized by the proliferation of keratinizing squamous epithelium resulting in the accumulation of keratin and cells in the middle ear and/or mastoid. "TREM-2 deficiency impaired the maturation of experimentally acquired cholesteatoma and protected against bone destruction induced by experimentally acquired cholesteatoma." (PMID 27934908, 2016). "Furthermore, TREM-2 deficiency impairs the maturation of experimentally acquired cholesteatoma, which decreases proinflammatory cytokine and MMP secretion and diminishes osteoclast formation in vivo." (PMID 27934908, 2016). "First, in human acquired cholesteatoma, bacterial infection induces high TREM-2 expression on the surface of DCs, which results in abundant IL-β and IL-6 secretion and amplifies the inflammatory response." (PMID 27934908, 2016). "WT and TREM-2−/− mice were used to establish experimental acquired cholesteatoma models and further explore the role of TREM-2 in the pathogenesis of acquired cholesteatoma." (PMID 27934908, 2016). "In human acquired cholesteatoma tissues, TREM-2 is significantly up-regulated on the surface of dendritic cells, and its expression is positively correlated with bone destruction, proinflammatory cytokine, and MMP levels." (PMID 27934908, 2016). "Real-time PCR revealed that TREM-2 expression was significantly up-regulated in human acquired cholesteatoma (n = 11) compared with the normal skin (n = 11) (p < 0.001)." (PMID 27934908, 2016). "Our study proved that TREM-2 was mainly expressed on the surface of DCs in human acquired cholesteatoma, which meant that it was likely to amplify the inflammatory response." (PMID 27934908, 2016). "In our study, TREM-2 was significantly up-regulated in human acquired cholesteatoma and positively correlated with the bone destruction level, which showed that TREM-2 might have a significant effect on this process." (PMID 27934908, 2016). "Therefore, we believed that TREM-2 amplified the inflammatory response in experimentally acquired cholesteatoma via the TLR4 signaling pathway." (PMID 27934908, 2016). "Based on the studies by other researchers, the reported roles of TREM-2 prompted us to propose the hypothesis that TREM-2 was likely to play a critical role in the development of human acquired cholesteatoma and bone destruction." (PMID 27934908, 2016). "In an animal model, TREM-2 was up-regulated in mice with experimentally acquired cholesteatoma." (PMID 27934908, 2016). "Therefore, it could be inferred that TREM-2 might amplify the inflammatory response in human acquired cholesteatoma and then increase the proinflammatory cytokines levels (IL-1β, TNF-α, and IL-6) while promoting MMP secretion." (PMID 27934908, 2016). "However, the expression and function of TREM-2 remain undiscovered in acquired cholesteatoma." (PMID 27934908, 2016). "Currently, there are no studies exploring whether TREM-2 is expressed in human acquired cholesteatoma or its association with bone destruction." (PMID 27934908, 2016). "Therefore, we speculated that TREM-2 is up-regulated and is responsible for bone destruction in human acquired cholesteatoma via the TLR4 pathway, based on the results of this study." (PMID 27934908, 2016). "Therefore, TREM-2 might enhance acquired cholesteatoma-induced bone destruction by amplifying the inflammatory response via TLR4 signaling pathways and promoting MMP secretion and osteoclast activation." (PMID 27934908, 2016). "Firstly, although several past studies on cholesteatoma explored not only MMP2 but also IL-6, other MMPs, TREM-2, and EGFR, this study focused only on the expression of MMP2 mRNA." (PMID 33778077, 2021). "TREM2 amplifies the inflammatory response of the TLR4 signaling pathway, promoting the secretion of MMP-2 and MMP-8 and the excessive activation of osteoclasts, thereby facilitating bone destruction induced by acquired cholesteatoma." (PMID 40242752, 2025).
cholesteatoma (continued). "In human acquired cholesteatoma, the expression of proinflammatory cytokines (IL-1β, TNF-α and IL-6) and matrix metalloproteinases (MMP-2, MMP-8 and MMP-9) were up-regulated, and their expression levels were positively correlated with TREM-2 expression." (PMID 27934908, 2016).
chronic obstructive pulmonary disease (3 papers, 2020 to 2025). A chronic and progressive lung disorder characterized by the loss of elasticity of the bronchial tree and the air sacs, destruction of the air sacs wall, thickening of the bronchial wall, and mucous accumulation in the bronchial tree. "In chronic obstructive pulmonary disease and colonic epithelial injury, TREM2 inhibits the expression of M1-activated markers and promotes M2 activation, which is important for colonic epithelial healing." (PMID 38236825, 2024). "Outside the CNS, TREM2 may play important roles in chronic obstructive pulmonary disease (COPD), gut injury, and infections." (PMID 32957083, 2020).